Y_RNA (Y RNA )
Gene: Miscellaneous RNA gene on chromosome 8 (100,158,868 to 100,158,975, forward strand). Ensembl gene ENSG00000202310.
Homologues: Orthologues: chimpanzee Y_RNA (99% identical), macaque Y_RNA (94% identical). Paralogues in human: RNY1P11 (86% identical), RNY1 (85% identical), Y_RNA (84% identical), Y_RNA (83% identical), RNY1P10 (82% identical), Y_RNA (82% identical), RNY1P8 (81% identical), Y_RNA (81% identical), RNY1P12 (80% identical), Y_RNA (80% identical), Y_RNA (79% identical), RNY1P5 (78% identical), and 96 more.